PTCH1 (patched 1)
Diseases named in the same sentence as PTCH1 in open-access papers (continued):
Sharing a sentence is not in itself a finding about the gene and the disease.
tumor (continued). "Examination of main Hh target genes individually shows higher levels of GLI2, PTCH1, SMO, BOC, and HHIP transcripts in the tumor-adjacent tissue as compared to the bulk tumor, further supporting the importance of the tumor-adjacent tissue in the activity of Hh signaling." (PMID 31658643, 2019). "The results of the present study indicated the gene expression of these important factors in the Hedgehog signaling pathway, such as DHH, GLI1, and PTCH1, was changed by the knockdown of AE1, suggesting that AE1 regulates the tumor behavior of ESCC via this pathway." (PMID 28160546, 2017). "We observe that the whole balance between division, differentiation and death is disrupted in Ptch1 heterozygous GCPs lacking Tis21, leading to an increase in tumor incidence." (PMID 27965576, 2016). "As we find that CDON is expressed in the tumour cell compartment, this leaves a possible tumour-promoting role for a non-canonical SHH/CDON/PTCH1 axis, acting independently of downstream Hh signalling." (PMID 27492255, 2016). "The HH signaling pathway receptor PTCH1 was found in normal duct epithelia, but was absent in tumor cells." (PMID 27783689, 2016). "Comparing papCP and adaCP tumor samples, the latter showed significant up-regulation of direct targets of the Wnt/β-catenin signaling pathway (LEF1 and AXIN2) as well as important components of the hedgehog signaling pathway (GLI2, PTCH1 and SHH)." (PMID 26927026, 2016). "One tumor (case 5) showed MYCN and MYCL amplifications, and a 9q deletion encompassing PTCH1; no chromothripsis was seen in that tumor." (PMID 26857864, 2016). "Formalin-fixed paraffin-embedded tumor tissues were collected from 338 M0 patients (>4.0 years at diagnosis) for pathology review and assessment of the WNT subgroup (MBWNT) and genomic copy-number defects (chromosome 17, MYC/MYCN, 9q22 (PTCH1) and DNA ploidy)." (PMID 26420814, 2015). "Mutant Ptch1 with diminished or absence of tumor suppressor activity results in the growth of BCCs in humans as well as in experimental animal models." (PMID 26413810, 2015). "Next, we detected PTCH1 in PDAC tissues and corresponding non-tumor tissues." (PMID 24961235, 2014). "In summary, while the miR-17∼92 and miR-106b∼25 clusters are essential for cerebellum development and homeostasis, the miR-17∼92, but not the miR-106b∼25, cluster is required for tumor initiation in Ptch1+/− mice." (PMID 24928431, 2014). "Furthermore, Chaudary and colleagues correlated the gene expression of different Hh components (SHH, IHH, PTCH1, PTCH2, GLI1) with clinicopathological data (tumor hypoxia, local recurrence and DFS) from cervical adenocarcinoma samples after CRT." (PMID 23880852, 2013). "Although this tumor etiology has been intensively investigated in the well-established Ptch1+/− mouse model, knowledge is still lacking about the molecular interactions between neoplastic transformation and other developmental processes." (PMID 22438824, 2012). "PTCH1 and PTCH2 were under-expressed in, respectively, 31.0 and 43.7% of tumour samples." (PMID 22361633, 2012). "As previously noted, JJ012 is reported to have a consistent chromosome 9 monosomy, and this is significant given that a number of important tumour suppressor genes occupy this locus, including INK4A/ARF, PTCH1, and the more recently described RECK gene which is downregulated in many common cancers." (PMID 20584302, 2010). "In respect to non-tumor control, relative fold reduction in expression of these genes in primary tumors was seen in the following order: FANCC (31.6 ± 36.7) > PHF2 (26.54 ± 44.41) > PTCH1 (19.3 ± 27.8)." (PMID 18990233, 2008).
tumor (continued). "PTCH1 is a receptor for SHH, and the activation of SHH signaling exerts a direct effect on the proliferation and maintenance of stem cells; alteration of its signaling could promote a favorable microenvironment for the maintenance of tumor viability." (PMID 40729247, 2025). "Considering that PTCH1 HH dependent upregulation comprises a negative feedback mechanism, this effect induced by 38 could have a highly beneficial anti-tumor effect." (PMID 40651614, 2025). "According to a study on medulloblastoma, non-ciliated cells, even those with constitutively active SMO, could not develop tumours, whereas ciliated precursor cells lacking PTCH1 were capable of developing tumours." (PMID 39234399, 2024). "Interestingly, in the healthy tissues, the stromal compartment was more often positive for PTCH1 than the epithelial compartment (p = 0.0025), while this was not the case when comparing the tumor and the tumor stroma compartment." (PMID 38731849, 2024). "Although there is a lack of PTCH1 expression studies from peripheral blood leukocytes, mRNA expression from tumor tissue describes an overexpression in various types of cancer and even a significant correlation with metastasis, resistance to therapy, and advanced stages of the disease." (PMID 38287479, 2024). "Reinforcing the specialized nature of the inflammation, we interrogated whether our mouse BCC scRNA-Seq datasets from our defined Ptch1+/−;p53f/f;K14Cre-ER;RFPf-s-f BCC tumor model that we found typically models many aspects of clinical BCCs34,35 also possessed BIT-associated inflammation." (PMID 39289380, 2024). "The trend seen in all samples is again seen here in the sinonasal adenocarcinoma subgroup, with PTCH1 expression significantly different between the healthy epithelium and healthy stroma (p < 0.0001), and GLI2 expression significantly different between the tumor and tumor stroma (p = 0.030)." (PMID 38731849, 2024). "Furthermore, overexpression of GLI1, GLI2, PTCH1, and SMO was correlated with a higher histological grade of the tumor, what may suggest that HH signaling plays a key role in HNSCC malignancy." (PMID 37626893, 2023). "Following our findings that PTCH1 reduces autophagic flux through its CTD, we hypothesised that its interaction with ATG101 is important for the tumour suppressor activity of PTCH1, which is mainly ascribed to its function to reduce GLI1 levels via regulation of the canonical Hh pathway." (PMID 36672319, 2023). "Interestingly, a novel PTCH1::GLI2 fusion rather than MALAT1-GLI1 fusion was detected in the tumor by RNA-based next generation sequencing (NGS)." (PMID 36147912, 2022). "However, when considering only prospectively collected data and multivariable tests, FANCC (LRR, HR = 6.6, CI [2.99–19.05], p = 0.0002), circulating tumor cells (CTC) (DFS, HR 4.3, CI [1.7–10.9], p = 0.002) and PTCH1 (LRR, HR = 5.98, CI [2.37–15.07], p = 0.0001) showed the strongest associations." (PMID 36552043, 2022). "Mutations within the components of the HH pathway, for example, membrane receptor proteins PTCH1 and SMO, non-membrane receptor proteins, such as SUFU and REN (KCTD11), disrupt the feedback loop causing activation of HH pathway and tumor progression." (PMID 33637972, 2021). "As BCC growth merely depends on epithelial Hh-pathway activation, it was tempting to test whether homozygous inactivation of Ptch1 exclusively in stromal cells would be sufficient to induce de novo HFs without tumor development." (PMID 32178760, 2020).
tumor (continued). "Noteworthy, by immunohistochemical analysis, we also evaluated in tumors and preneoplastic lesions of Ptch1+/−/Btg1WT and Ptch1+/−/Btg1KO mice the expression of Sox2, a marker for tumor stem cells in Shh-induced MB, without finding any difference (data not shown)." (PMID 32231994, 2020). "Thus, in tumours cells lacking PTCH1, SMO is constitutively active and HH pathway activity remains elevated." (PMID 30068568, 2018). "However by week 30, 20% or less of the age-matched control non-irradiated Ptch1+/−/SKH-1 mice had developed spontaneous BCCs (0.25 ± 0.12 tumor/mouse)." (PMID 26413810, 2015). "Next generation sequencing of these tumours showed large on-site deletions disrupting the Ptch1 locus whereas no off-target could be detected." (PMID 26067104, 2015). "At the endpoint of the experiment, no statistically relevant difference in human (tumor) or mouse (stroma) Ptch1 or Gli1 mRNA levels could be identified in the extracted tumor mRNA (P>0.05)." (PMID 21698280, 2011). "In addition, we found that even in the tumor with elevated expression of hedgehog target genes Gli1 and PTCH1, expression of SHH is not necessarily high, suggesting other mechanisms of hedgehog signaling activation in the cancer." (PMID 19943941, 2009). "Similarly, the SHH transcript is localized to tumor tissue whereas GLI1 and PTCH1 are detected in both the tumor and the stroma, proving the hypothesis that SHH and its target genes function in a paracrine manner to regulate the development of subsets of esophageal cancers." (PMID 30423843, 2018). "In addition, the authors found that even in the tumor with elevated expression of the hedgehog target genes Gli1 and PTCH1, expression of Shh is not correlated with Hh target gene expression, suggesting other mechanisms of hedgehog signaling activation in this particular cancer type." (PMID 23303278, 2013). "As PTCH1 may shuttle between the cell membrane and endocytotic vesicles in response to active hedgehog ligand, it is obvious that not only its mRNA expression, but also its protein expression (at the relevant location, binding of SMO, etc.)is necessary to exert its tumour suppressor activity." (PMID 17173689, 2006). "Independent of tumor characteristics, such as histology and grades, higher expressions of SHH, PTCH1, PTCH2, and GLI1 have shown beneficial prognostic influence, whereas GLI2, GLI3, and SUFU are correlated with adverse clinical outcomes in OC patients." (PMID 40565349, 2025). "Both PTCH1 and GLI1 were observed in more than 50% of tumor tissues, and a higher ratio of GLI1 mRNA in HCC/noncancerous liver was significantly correlated with recurrence and short overall survival (OS)." (PMID 33440657, 2021). "Examination of Hh transcripts indicate that tumor growth suppression correlates with down-regulation of GLI1, PTCH1, and SMO transcripts in cells of mouse but not of human origin." (PMID 31658643, 2019). "For instance, Ptch1 triggers both a canonical and non-canonical signaling pathways, and can synergize with PI3K pathway to promote tumor growth and viability in GBM." (PMID 26635611, 2015). "Henceforth, changes observed in the behavior of Luminal A cell lines treated with Hh inhibitors did not correlate with suppression of GLI1, PTCH1, and SMO transcripts, thus changes observed in tumor cell behavior are likely the result of off-target effects or non-canonical Hh signaling mechanisms." (PMID 31658643, 2019).
tumor (continued). "However, while PTCH1 and GLI1 were expressed in all metastatic tumor samples, only 3 out of 12 localized tumor samples and none of the benign tissue samples expressed these genes." (PMID 23880852, 2013). "More specifically, tumor-promoting target genes, e.g. MMP7/9, IL-8 and VEGFA, were synergistically upregulated, while intriguingly negative modulators of HH/GLI signaling, such as HHIP and PTCH1, were downregulated." (PMID 23762360, 2013). "However, such an approach has proven challenging because even though Ptch1+/− mouse tumors depend on Smo for RMS initiation, the SMO inhibitor cyclopamine does not appear to suppress tumor growth in vivo." (PMID 22619564, 2012). "Additionally, the involvement of GLI1 downstream target genes such as PTCH1, Cyclin D2, Plakoglobin, NKX2.2 and PAX6 have not been studied in either tumor." (PMID 21059263, 2010).
cancer (198 papers, 2009 to 2026). A tumor composed of atypical neoplastic, often pleomorphic cells that invade other tissues. "Interstitial chromosomal deletions have been used for cancer-risk assessment for low-dose radiation exposure using the Ptch1+/− mouse model." (PMID 41007286, 2025). "PTCH1 mutations are frequent drivers of cancers such as BCC and medulloblastoma, and Hh pathway mutations are common across many different cancer types." (PMID 40301543, 2025). "Our findings suggest that mutations in the CTD of PTCH1, relatively common in some epithelial cancer types, contribute to cancer cell fitness by loss of PTCH1 regulation of autophagy and increase in metabolic flexibility under nutritional stress." (PMID 36672319, 2023). "Immunoprecipitation of the PTCH1 variants using the common myc-tag showed that the interaction of ATG101 is abolished in all cancer-associated PTCH1 CTD truncation mutants." (PMID 36672319, 2023). "With the only exception of PTCH1, 6/7 (85.8%) of these cancer-associated genes have been described to be associated with NSCLC development." (PMID 35723337, 2022). "The same lncRNA was observed in 24 LSCC samples and cells, targeting miR-425-5p and subsequently targeting PTCH1, affecting the Hedgehog pathway and its downregulation was associated with increased cancer stemness and chemoresistance to cisplatin." (PMID 35978835, 2022). "Truncating variants were also detected in two lesser-known cancer susceptibility genes, namely PTCH1 (NM_000264.5):c.4187delG, p.Gly1396AspfsTer56 and KIT (NM_000222.3):c.930delA, p.Gly311AspfsTer8." (PMID 36568162, 2022). "Molecular link of Hh signaling with cancer was reported in basal cell carcinoma when mutation in human PTCH1 gene was observed." (PMID 33489917, 2020). "The first significant breakthrough in understanding the role of SHH signaling in cancer progression was the discovery that mutations in the PTCH1 gene were responsible for Gorlin-Goltz syndrome." (PMID 32545245, 2020). "According to this idea, NBCCS fibroblasts, sharing with keratinocytes the same PTCH1 germline mutation and consequent constitutive activation of the Hh pathway, display features of carcinoma-associated fibroblasts (CAF)." (PMID 31979112, 2020). "The PTCH1 mutation burden was correlated with TILs, intrinsic subtypes, prognostic predictors, and cancer recurrence by PheWAS analysis." (PMID 31704974, 2019). "Activation of Hh signaling in cancer can occur via several mechanisms, such as ectopic production of Hh ligands, somatic mutations in the Hh pathway components, Ptch1, Smo, Sufu, and/or amplifications of the Hh transcription factor Gli1." (PMID 31137846, 2019). "This makes Ptch1 a particularly attractive therapeutic target to enhance the effectiveness of classical chemotherapeutic treatments, and to decrease the risk of recurrence and metastasis in cancers expressing Ptch1." (PMID 30110910, 2018). "One such drug, Vismodegib, is licensed by the FDA for the treatment of advanced or metastatic cases of BCC, cancer driven by PTCH1 mutations." (PMID 30379908, 2018). "The first hint, that the Hh pathway makes a critical contribution to cancer development, came from the studies describing mutations in PTCH1 gene in BCC." (PMID 29695137, 2018). "As local stromal loss of Ptch1 and non-epithelial activation of Smo promote a DCIS-like phenotype in mammary epithelium, perhaps stromal Ptch1 loss promotes cancer-associated phenotypes." (PMID 28275010, 2017). "The major breakthrough in the understanding of Shh signaling in cancer came from the discovery that mutations in PTCH1 were the cause of Gorlin syndrome suggesting that aberrant Shh pathway activity was responsible for the development of these cancers." (PMID 26891329, 2016). "First, canonical Hh signaling in cancer is quite limited to tumors with gene mutations in PTCH1 and SMO, which will be sensitive to SMO signaling inhibitors." (PMID 26343727, 2015).